NOTCH2 (notch receptor 2)
Diseases named in the same sentence as NOTCH2 in open-access papers (continued):
Sharing a sentence is not in itself a finding about the gene and the disease.
choroid plexus tumors (2 papers, 2019 to 2023). "Different from Notch2, Notch3 has been implicated in choroid plexus tumors, and knockdown of Notch3 only slightly affect the viability of U87 cells,which is consistent with our observation." (PMID 30606241, 2019).
cryptorchidism (2 papers, 2018 to 2025). The failure of one or both testes of a male fetus to descend from the abdomen into the scrotum during the late part of pregnancy. "The only patient with a NOTCH2 variant (P21) displayed a complex genotype that includes cleft lip and palate, hypospadias, cryptorchidism, and conductive hearing loss." (PMID 40806755, 2025). "Hypospadias and cryptorchidism are common findings in patients affected by NOTCH2 variants, compared to those with JAG1 variants." (PMID 40806755, 2025). "Both appear to be essential for proper cell differentiation during testicular development, although there has been no reported case of cryptorchidism caused just by mutation in NOTCH2 gene, but it's contribution to reported, more complex cases, cannot be excluded." (PMID 30093884, 2018).
cystic kidney disease (2 papers, 2019 to 2022). A congenital or acquired kidney disorder characterized by the presence of renal cysts. "Genetic deletion of Notch1 or Notch2 resulted in renal cysts by three weeks of age, but ablation of Notch1 or Notch2 simultaneously, or of RBP-J, resulted in renal cysts at birth." (PMID 35055068, 2022). "ALGS patients with the same NOTCH2 mutation may have no renal defects, or congenital cystic kidney disease or late adult onset kidney disease." (PMID 31690016, 2019).
dyslipidemia (2 papers, 2022). "Four proteins linked to lipid levels, including NOTCH2, were inversely associated with the LIPID-pGRS, which suggests that low levels of these proteins were associated with high LIPID-pGRS and a higher risk of dyslipidemia." (PMID 35106505, 2022).
focal segmental glomerulosclerosis (2 papers, 2022). A renal disorder characterized by sclerotic lesions in the glomeruli. "In kidneys affected by congenital nephrotic syndrome of the Finnish type (CNF) and focal segmental glomerulosclerosis (FSGS), WNT4 decreased in both cell populations, whereas Notch2 decreased in FSGS." (PMID 35886848, 2022).
follicular lymphoma (2 papers, 2020 to 2022). Follicular lymphoma is a form of non-Hodgkin lymphoma characterized by a proliferation of B cells whose nodular structure of follicular architecture is preserved. "In human follicular lymphoma, pharmacological inhibition of BCL6 liberates NOTCH2 expression, resulting in apoptosis." (PMID 35536646, 2022).
gallbladder cancer (2 papers, 2017 to 2021). "It is also likely that Kras- mediated Notch deregulation promotes tumor development in a subset of gallbladder cancer patients, and targeting Notch2/3 and Jag1 could be a therapeutic approach for these patients." (PMID 29142904, 2017).
gastric adenocarcinoma (2 papers, 2016 to 2020). "The expression of Notch1, Notch2, Notch3 and Notch4 proteins, which were examined by immunohistochemistry, were higher in the gastric adenocarcinoma tissues than that in the normal gastric tissues." (PMID 32028262, 2020). "Constitutive expression of Notch2 NICD promoted both cell proliferation and xenografted tumor growth of human gastric adenocarcinoma SC-M1 cells." (PMID 27363496, 2016).
glomerular disease (2 papers, 2010 to 2022). "Upon completion of the glomerular development, Notch2 signaling decreases significantly in podocytes but increases in many patients and models of glomerular disease." (PMID 35886848, 2022).
hemangioma (2 papers, 2023 to 2024). A benign vascular lesion characterized by the formation of capillary-sized or cavernous vascular channels. "Inhibits the proliferation and induces the ferroptosis of hemangioma endothelial cells by regulating miR-497-5p/NOTCH2 axis." (PMID 39267831, 2024). "In addition, NOTCH2 is regulated by silencing long-chain noncoding RNA MEG8 to induce ferroptosis in hemangiomas." (PMID 37978473, 2023).
Hepatic steatosis (2 papers, 2022 to 2024). Steatosis is a term used to denote lipid accumulation within hepatocytes. "Gas5 was found to sponge miR-29a-3p and suppressed its negative regulation on the neurogenic locus notch homologue protein 2 (Notch2), a known promoter of hepatic steatosis, leading to the upregulation of Notch2." (PMID 39872125, 2024). "HFD-induced hepatic steatosis was enhanced by miR-29a-3p inhibitor, while NOTCH2 depletion reversed this effect." (PMID 35322757, 2022).
Hydrocephalus (2 papers, 2005 to 2025). Hydrocephalus is an active distension of the ventricular system of the brain resulting from inadequate passage of CSF from its point of production within the cerebral ventricles to its point of absorption into the systemic circulation. "Notch2 affects Wnt-1 expression, and in mouse the Wnt sw/sw mutant has defective SCO development and hydrocephalus." (PMID 15953386, 2005).
hypospadias (2 papers, 2019 to 2025). Hypospadias is the displacement of the urethral meatus on the ventrum of the penis. "Patient 7 presented five variants in five genes: EVC, MAML3, NOTCH2, PPARGC1B and WDR11; four of them associated with hypospadias or male gonadal development and one, MAML3, with female gonadal development." (PMID 31555317, 2019). "In patient 5, six variants in six genes were found: BNC2, FGF10, HSD3B2, IRX5, MAML2 and NOTCH2; all, except MAML2, have also been associated with hypospadias or gonadal development." (PMID 31555317, 2019).
intervertebral disc degeneration (2 papers, 2019 to 2022). "Previously, JAG2/Notch2 axis has been reported to alleviate intervertebral disc degeneration (IVDD) by modulating apoptosis, proliferation, and the extracellular matrix of nucleus pulposus cells." (PMID 36035989, 2022).
intestinal tumors (2 papers, 2011 to 2015). "Multivariate analysis in intestinal tumors indicated R-status (HR: 2.78, 95% CI: 1.39–5.55, p = 0.004) and tumor stage (HR: 2.61, 95% CI: 1.28–5.30, p = 0.008) as independent prognostic factor but not NOTCH2 expression." (PMID 25954607, 2015).
Jaundice (2 papers, 2017 to 2024). Yellow pigmentation of the skin due to bilirubin, which in turn is the result of increased bilirubin concentration in the bloodstream. "Double heterozygous mice of Jag1 and Notch2 display jaundice associated with defects in bile duct epithelial cell differentiation and morphogenesis." (PMID 29142904, 2017).
lymph node metastasis (2 papers, 2023 to 2025). "In CRC, elevated Notch1 expression is associated with lymph node metastasis, while reduced Notch2 expression predicts poor prognosis." (PMID 40438109, 2025).
MALT lymphoma (2 papers, 2021 to 2022). An indolent, extranodal type of non-Hodgkin lymphoma composed of small B-lymphocytes (centrocyte-like cells). "Four genes recently described to be mutated in the non-pSS MALT lymphoma of the salivary gland, TBL1XR1, CCR6, TNFAIP3 and NOTCH2, were also mutated in a subset of our pSS-MALT lymphomas." (PMID 35205758, 2022). "Recurrent mutations have been described in NOTCH1 and NOTCH2, but mainly in MALT lymphomas of the ocular adnexa (8–10%) and dura (29%)." (PMID 35008340, 2021).
nephrotic syndrome (2 papers, 2018 to 2021). A collection of symptoms that include severe edema, proteinuria, and hypoalbuminemia; it is indicative of renal dysfunction. "Mice with the Adriamycin-induced nephrotic syndrome also showed increased expression of activated NOTCH2, which ameliorates fibrosis." (PMID 33924028, 2021). "It is important to note that isoform-specific Notch-receptor targeting has been more difficult to develop than ligand targeting; furthermore, one study examining the role of Notch2 in podocytes in nephrotic syndrome indicated some potential benefit." (PMID 30226866, 2018).
Parkinson disease (2 papers, 2018 to 2024). A progressive degenerative disorder of the central nervous system characterized by loss of dopamine producing neurons in the substantia nigra and the presence of Lewy bodies in the substantia nigra and locus coeruleus. "Expression levels of NOTCH2, H4C8, and H2BC21 in the substantia nigra of Parkinson’s disease patients effectively distinguish them from controls." (PMID 39457375, 2024).
Premature ovarian insufficiency (2 papers, 2020 to 2021). Amenorrhea due to loss of ovarian function before the age of 40. "It has also been shown that downregulation of CAV-1 gene expression in female ovaries pathway affects the Notch2 signaling and causes a decrease in Leucine-rich repeat containing G protein-coupled receptor 5 (Lgr5) leading to POI (premature ovarian insufficiency)." (PMID 34827207, 2021).
prostate tumor (2 papers, 2011 to 2015). "Moreover, PEITC administration causes significant increase in nuclear levels of cleaved Notch2 in vivo in prostate tumors from two different rodent models." (PMID 22039516, 2011). "Prostate was the most frequently mutated cell type for both NOTCH1 and NOTCH2 but prostate tumor cell lines did not contain any mutations in NOTCH3 or NOTCH4 (right hand side)." (PMID 25907971, 2015).
renal cell carcinoma (2 papers, 2023 to 2024). "Among them, the NOTCH2 gene was related to cell stemness, which could induce and regulate the occurrence and apoptosis of tumor cells; NT5E could inhibit the growth, EMT process, and AKT/GSK-3β signaling pathway of sunitinib-resistant cells in renal cell carcinoma." (PMID 38730456, 2024).
skin cancer (2 papers, 2007 to 2010). "However, double Notch1 and Notch2 knockout mice (Pdx1-Cre;Kras;N1ko;N2ko) featured an accelerated skin tumor formation suggesting an essential role of Notch1 ablation in epidermal lesion development and a promoting role of Notch2 deletion." (PMID 21042537, 2010). "Further analysis revealed that loss of Notch1 but not Notch2 is critical for skin tumor development." (PMID 21042537, 2010). "In our study, Pdx1-Cre;Kras;N1ko but not Pdx1-Cre;Kras;N2ko or Pdx1-Cre;Kras developed skin lesions which points to the importance of Notch1 but not Notch2 for skin tumor development." (PMID 21042537, 2010).
squamous cell carcinoma (2 papers, 2010 to 2022). A carcinoma arising from squamous epithelial cells. "This is particularly evident in various forms of squamous cell carcinomas, where, for example, 70–80% of skin squamous cell carcinoma tumors exhibit loss-of-function NOTCH1 or NOTCH2 mutations." (PMID 35682918, 2022). "Surprisingly, mice with activated KrasG12D and Notch1 but not Notch2 ablation developed skin papillomas progressing to squamous cell carcinoma providing evidence for Pdx1 expression in the skin." (PMID 21042537, 2010).
systemic sclerosis (2 papers, 2023 to 2024). A chronic disorder, possibly autoimmune, marked by excessive production of collagen which results in hardening and thickening of body tissues. "It has been reported a reduction in miR-16-5p expression and an increase in NOTCH2 expression among systemic sclerosis patients." (PMID 38191820, 2024).
Tetralogy of Fallot (2 papers, 2014 to 2017). A congenital cardiac malformation comprising pulmonary stenosis, overriding aorta, ventricular septum defect, and right ventricular hypertrophy. "Mutations in Notch-2 gene that results in deficiency of Notch-2 signaling are associated with congenital heart defects including right-sided obstructive lesions such as pulmonary artery stenosis and tetralogy of Fallot, as well as ventricular septal defects." (PMID 28408970, 2017).
Ureteral obstruction (2 papers, 2017 to 2025). Obstruction of the flow of urine through the ureter. "In a unilateral ureteral obstruction (UUO)-induced CKD mouse model and a TGF-β1-stimulated HK-2 cell model, ICA significantly inhibited Notch2/Hes-1 pathway activity and downregulated Notch2 mRNA levels, indicating a strong anti-fibrotic potential." (PMID 40872565, 2025).
actinic keratosis (1 paper, 2025). A precancerous lesion of the skin composed of atypical keratinocytes.
acute graft versus host disease (1 paper, 2024). A syndrome of immunologically mediated tissue damage that may occur following an allogeneic transplant, usually affecting the skin, liver, and GI tract. "Recently, a contribution to the severity of T-cell-mediated acute graft-versus-host disease in mice was shown via the OTUD1-dependant accumulation of Notch2-ICD, inducing a shift towards the pro-inflammatory Th17 phenotype." (PMID 39201568, 2024).
acute liver failure (1 paper, 2016). Rapid deterioration of liver function causing encephalopathy and coagulopathy. "Another study performed whole exome sequencing in three children with acute liver failure and identified pathogenic mutations in MPV17, SERAC1 and NOTCH2, despite the lack of characteristic clinical phenotypes for these genes." (PMID 27053192, 2016).
acute lymphoblastic leukemia (1 paper, 2020). Leukemia with an acute onset, characterized by the presence of lymphoblasts in the bone marrow and the peripheral blood. "Accordingly, elevated Notch1 signaling is oncogenic in T cells driving acute lymphoblastic leukemia (T-ALL), whereas increased Notch2 signaling is associated with splenic MZB transformation." (PMID 33017398, 2020).
adenoid cystic carcinoma (1 paper, 2019). A malignant tumor arising from the epithelial cells. "Similarly, in adenoid cystic carcinoma, mutations in NOTCH1 and NOTCH2 have been identified as altered targets in various genomic screenings, and knock-down of Notch1 or Notch2 inhibits proliferation of adenoid cystic carcinomas in models of the disease." (PMID 31455013, 2019).
ALAGILLE syndrome type 2 (1 paper, 2023). "The deletion of exons 2–4 in the NOTCH2 gene may lead to HAJDU-CHENNEY syndrome (OMIM: 102500) and ALAGILLE syndrome type 2 (OMIM: 610205)." (PMID 38075692, 2023).
allergic rhinitis (1 paper, 2026). Inflammation of the nasal mucous membranes caused by an IgE-mediated response to external allergens. "Here, we elucidate the mechanisms through which Notch2 influences aTreg dynamics and mitigates allergic rhinitis (AR) development." (PMID 41524129, 2026).
ameloblastoma (1 paper, 2020). The most common odontogenic tumor, arising from the epithelial component of the embryonic tooth and usually affecting the molar-ramus region of the mandible or maxilla. "NOTCH3 expression partially overlapped with that of NOTCH2, as it was detected at the interface between the ameloblastoma epithelium and the underlying stroma." (PMID 32155948, 2020). "Expression of NOTCH2 and NOTCH3 was associated with expression of the ligands JAG1, DLL1, and DLL4 in the ameloblastoma epithelium." (PMID 32155948, 2020). "Here, we showed that NOTCH2 and NOTCH3, but not NOTCH1 (data not shown), are expressed at the interface between the ameloblastoma epithelium and the underlying stroma, which is a location pivotal for the acquisition of an invasive phenotype." (PMID 32155948, 2020).
ampullary cancer (1 paper, 2015). "The Notch pathway is located upstream of nestin and the NOTCH2 and NOTCH3 genes were overexpressed in ampullary cancer." (PMID 25371063, 2015).
angioimmunoblastic T-cell lymphoma (1 paper, 2021). A mature T-cell non-Hodgkin lymphoma, characterized by systemic disease and a polymorphous infiltrate involving lymph nodes and extranodal sites. "The NOTCH2 C19W mutation has been reported in angioimmunoblastic T cell lymphoma." (PMID 34299796, 2021).
aortic valve disease (1 paper, 2019). "The genesis of aortic valve disease can be induced by deletion mutation of Notch2 signal transduction function." (PMID 30923228, 2019).
atherosclerosis (1 paper, 2022). A disease characterized by the build-up of fatty material and calcium deposition in the arterial wall resulting in partial or complete occlusion of the arterial lumen. "In macrophages isolated from patients with atherosclerosis, NOTCH1 appears to play a more prominent role than those of NOTCH2 and NOTCH3 in the regulation of the NF-κB signaling pathway and in the induction of pro-inflammatory gene expression." (PMID 35891967, 2022).
autism spectrum disorder (1 paper, 2025). A spectrum of developmental disorders that includes autism, and Asperger syndrome. "NOTCH1, NOTCH2, and ANK2 have also been associated with mental disorders, such as autism spectrum disorder." (PMID 41157308, 2025).
benign gynecologic tumors (1 paper, 2025). "The best predictor of OC vs. benign gynecologic tumors was CTNNB1 expression (AUC = 0.95, accuracy = 0.86, sensitivity = 0.84, specificity = 1); however, the highest accuracy and sensitivity were detected by NOTCH2 (AUC = 0.89, accuracy = 0.89, sensitivity = 0.89, specificity = 0.89)." (PMID 40002854, 2025).
bladder urothelial carcinoma (1 paper, 2021). "Alterations in Notch 2 are frequently linked to cancer and bladder urothelial carcinoma having the greatest prevalence of Notch 2 alterations." (PMID 33460397, 2021).
brain cancer (1 paper, 2025). A primary or metastatic malignant neoplasm affecting the brain. "Hence, similar to adult brain where Notch-2 was shown to control quiescence of neuronal stem cells, Notch-2 may convey quiescence to brain cancer cells when HA molecular flexibility is low." (PMID 40881990, 2025).
brain glioma (1 paper, 2014). A malignant glioma that involves the brain. "In the present study, substantial levels of Notch2 mRNA and Notch2 protein expression were detected in U87 human brain glioma cells." (PMID 25323114, 2014).
carcinoma in situ (1 paper, 2022). "Studies on human testicular samples, which revealed a common expression of Notch2 and Notch4 receptors in seminoma and carcinoma in situ, raised the possibility that Notch signaling plays a role in controlling the mitotic/meiotic switch in primordial germ cells." (PMID 35216398, 2022).
cardiomyopathy (1 paper, 2023). A disease of the heart muscle or myocardium proper. "Microvascular network growth and the angiogenic properties of the TAT in elderly patients with cardiomyopathy also seem to involve the upregulation of PDGFC, FGF2, NOTCH2, FOS, JAG1, and PDGFRA target genes." (PMID 37833902, 2023).
chordoma (1 paper, 2013). Chordomas are rare malignant tumors arising from embryonic remnants of the notochord in axial skeleton. "Six genes (NOTCH2, NCOR2, CREBBP, JAG1, KAT2A and NCSTN) related to the Notch signaling pathway were upregulated in chordoma tissues." (PMID 23826111, 2013).
cocaine addiction (1 paper, 2017). "In the present study, we found both Wnt4 and Notch2 expression increased 2 h after withdrawal and their roles in cocaine addiction should be further investigated." (PMID 28386228, 2017).
colitis (1 paper, 2025). Inflammation of the colon. "As observed in the EAE model, we also identified CD4+Notch2+ T cells in the lamina propria region of the colitis model mice; this population also expressed the TCR." (PMID 40702356, 2025). "Most importantly, the CD4+Notch2+Foxp3lo T cells in the colitis model mice also expressed membrane−bound TNFα and TGF−β (LAP)." (PMID 40702356, 2025). "Moreover, CD4+Notch2+Foxp3lo T cells are present in the laminar propria of mice with experimental colitis and in that of humans with UC, whose population is phenotypically similar to that observed in an EAE mouse model." (PMID 40702356, 2025). "In this study, we identified CD4+Notch2+Foxp3lo T cells in the spinal cords of mice with experimental autoimmune encephalomyelitis (EAE), dextran sodium sulfate−induced colitis model mice, and patients with ulcerative colitis as immune regulatory cells." (PMID 40702356, 2025).
colorectal adenocarcinoma (1 paper, 2025). The most common type of colorectal carcinoma. "Cis-activation of Notch2 by DLL4 has already been demonstrated in cultured colorectal adenocarcinoma cells." (PMID 39951484, 2025).